S100P (S100 calcium binding protein P)
Diseases named in the same sentence as S100P in open-access papers (continued):
Sharing a sentence is not in itself a finding about the gene and the disease.
pancreatic cancer (continued). "MATN2 and SCGB2A2 are upregulated in ovarian cancer; S100P is upregulated in prostate cancer, invasive ductal carcinomas, and pancreatic cancer; LDHB is a biomarker for triple negative breast cancer; and TNC is associated with Tamoxifen resistance in breast cancer." (PMID 27449296, 2016). "Furthermore, in an investigation of the role of S100P in pancreatic cancer, one study revealed that cells with siRNA-silenced S100P expression grew at a significantly reduced rate compared with control siRNA-expressing cells." (PMID 24821384, 2014). "Our results are in line with a study that silenced S100P in pancreatic cancer as well as another study that silenced S100P expression in colon cancer as suppressing S100P expression also reduced the rate of migration and invasion in pancreatic and colon cancer." (PMID 24821384, 2014). "Likewise, S100P overexpression has been reported to promote pancreatic cancer growth and increase cell survival after 5-fluorouracil exposure." (PMID 20515499, 2010). "Up-regulation of S100P was reported in breast cancer, prostate cancer and early-stage non-small cell lung cancer, and it was also suggested to be a key factor in the aggressiveness of pancreatic cancer and promote cancer growth, survival and invasion." (PMID 19171046, 2009). "In summary, genes associated with past alcohol consumption have been linked to physiological processes associated with increased risk for malignant transformation, pancreatic cancer cell proliferation, survival, invasion, metastasis, and impaired cell differentiation (K19, IFI27, S100P, CXCR4)." (PMID 17181856, 2006). "Notably, the mRNA expression of S100P was significantly increased in patients with stage II-IV compared to patients with stage I, suggesting that S100P may potentially contribute to the progression of pancreatic cancer." (PMID 37853345, 2023). "The current review study identifies 22 IHC biomarkers as diagnostic tools for pancreatic cancer that embrace: Pentraxin-3, ENO1, REG4, POSTN, CA125, CA242, Galectin-1, Galectin-9, Maspin, pVHL, MUC1, MUC5AC, THBS2, LTBP2, CPA4, IMP3, CD13, Dkk1, KOC, S100P, Mesothelin, PAM4." (PMID 34988027, 2021). "Furthermore, evidence indicated that S100P could be a helpful marker for the diagnosis of pancreatic cancer, as it is specifically expressed in cancer cells." (PMID 32722137, 2020). "Also, S100P roles in tumorigenesis have been well-documented in pancreatic cancer." (PMID 27449296, 2016). "The S100P protein was first identified in the human placenta, and has been reported to be overexpressed in multiple types of cancer cells, including breast cancer, esophageal cancer, colon cancer, lung cancer, pancreatic cancer, prostatic cancer, ovarian cancer, cholangiocarcinoma, and HCC." (PMID 23785431, 2013). "The expression levels of S100P and cathepsin E (CTSE) were significantly higher in pancreatic cancer (PC) tissues than in adjacent normal tissues." (PMID 41301873, 2025). "In human pancreatic cancer cells and tumors, it has been demonstrated that both RAGE ligands, HMGB1 and S100P, stimulate RAGE." (PMID 38529373, 2024). "Two noteworthy RAGE ligands, namely, S100P and high mobility group box 1 (HMGB1), have undergone extensive examination in the context of pancreatic cancer." (PMID 39087024, 2024). "S100P, operating through a RAGE-dependent mechanism, stimulates the proliferation and migration of human pancreatic cancer Panc-1 cells." (PMID 39087024, 2024). "Among these S100 proteins, S100P and S100A4 have been most intensively investigated and both proteins have been shown to stimulate pancreatic cancer cell proliferation and tumor growth." (PMID 37627239, 2023). "Given that the high expression of S100P and low expression of S100PBP correlate with poor survival in PDAC patients, this study highlights the potential clinical relevance of S100PBP in pancreatic cancer." (PMID 37794133, 2023).
pancreatic cancer (continued). "The two RAGE ligands S100P and HMGB1 have been shown to stimulate RAGE in human pancreatic cancer cells and tumors and to promote pancreatic tumorigenesis." (PMID 33915939, 2021). "The most specific IHC biomarkers consist of Galectin-1, Maspin, KOC, and S100P, whereas MUC1 is the least specific IHC biomarker for the diagnosis of pancreatic cancer in the current review." (PMID 34988027, 2021). "A representative test set identified a number of structurally unrelated hits that inhibit S100P-RAGE interaction, measured by ELISA, and reduce in vitro cell invasion selectively in S100P-expressing pancreatic cancer cells at 10 μM." (PMID 32707527, 2020). "Two ligands of RAGE, S100P, and high mobility group box 1 (HMGB1), have been extensively studied in the context of pancreatic cancer." (PMID 33086527, 2020). "S100P-derived RAGE antagonistic peptide has been found to delay tumor growth and metastasis in pancreatic cancer." (PMID 29868478, 2018). "Cromolyn has been reported to bind S100P, prevent activation of RAGE, inhibit tumor growth, and increase the effectiveness of gemcitabine in pancreatic cancer experimental models." (PMID 26009899, 2015). "Confirmed genes included genes already reported in the literature and proposed as biomarkers of pancreatic cancer such as S100A6, TIMP1, NF-κB, VCL and S100P." (PMID 22078386, 2011). "This set included genes already reported in the literature as differentially expressed in pancreatic cancer and that have been investigated as biomarkers for pancreatic cancer (i.e. S100A6, S100P, TIMP1 and NF-κB)." (PMID 22078386, 2011). "However, q-PCR data on the S100P, MAPK11, CX3CL1, and PRDM16 genes in an in vivo pancreatic cancer model all show significant downregulation following QN-302 treatment (unpublished observations)." (PMID 39125057, 2024). "In addition to the receptor itself, RAGE ligands such as S100P and high mobility group box 1 (HMGB1) have been widely investigated for their roles in pancreatic cancer." (PMID 39796649, 2024). "Others have demonstrated that exogenous S100P has also been shown to increase the secretion of matrix metalloproteinase 9 (MMP-9) in pancreatic cancer cells although a role in cellular invasion was not shown." (PMID 37627296, 2023). "Using this approach and verifying the data using individual gene expression data, we found that AGR2, CEACAM6, GNMT, PDIA2, POSTN, RBPJL, and S100P are upregulated in pancreatic tumor tissue as compared to non-tumor tissue from Black and White patients." (PMID 36812168, 2023). "Non-SC markers for pancreatic cancer such as S100P, which is a small calcium binding protein with diverse normal regulatory functions and also promotes pancreatic cancer growth, tumor cell survival and invasion, are overexpressed in pancreatic cancers." (PMID 22626610, 2012). "Thus, regulating S100P expression through inhibitors could facilitate TME remodeling and provide potential therapeutic interventions for pancreatic cancer." (PMID 37853345, 2023). "Additionally, the UALCAN dataset also demonstrated a significant increase in S100P expression in pancreatic cancer tissues, as compared to normal tissues (P < 0.05)." (PMID 37853345, 2023). "Our observations with S100P, where transcripts could only be detected in the cancer cell lines and not in the HPNE control cell line, are also in agreement with many studies that demonstrated the involvement of this S100 in the progression of pancreatic cancer." (PMID 37627239, 2023). "Using data from pancreatic cancer patient samples from The Cancer Genome Atlas (TCGA), we demonstrated that although there was no change in the expression of RAGE, the RAGE ligands, S100P and S100A2, were significantly increased in pancreatic tumors when compared to normal pancreatic tissue." (PMID 39796649, 2024).
pancreatic cancer (continued). "However, the animal model used by the authors does not express functional S100P, suggesting that HMGB1 activation of RAGE can stimulate pancreatic cancer cells and promote their proliferation." (PMID 38529373, 2024).
breast carcinoma (52 papers, 2005 to 2025). "According to authors, overexpression of the S100P protein has been linked to both the in vitro immortalization of human breast epithelial cells and the in vivo early phases of breast cancer development." (PMID 39594999, 2024). "Consistent with our findings, other groups also reported the association of S100P mRNA and protein expression with worse breast cancer outcomes." (PMID 37445737, 2023). "Our previous work demonstrated that S100P promotes cell migration and induces metastasis in an animal model of breast cancer, and that elevated levels of S100P in primary human breast cancer are associated with shorter patient survival times." (PMID 32065231, 2020). "S100P is reported to induce metastatic phenotype transformation in a benign rat mammary tumor model, and S100P overexpression is associated with immortalization of human breast epithelial cells in vitro." (PMID 32596149, 2020). "Recently, S100P hypomethylation in blood was demonstrated to be inversely correlated with tissue S100P expression and significantly associated with breast cancer, implicating S100P as a potential diagnostic marker." (PMID 30616553, 2019). "S100P is a calcium-binding protein with a number of cellular functions which has been directly associated with metastasis and poor survival in breast cancer." (PMID 30670058, 2019). "Our results indicated that S100A9, S100A11 and S100P were associated with worse outcome in all breast cancer patients according to the Kaplan-Meier survival curves and the log-rank P value based on the database." (PMID 28051137, 2017). "S100P high mRNA expression was associated with worse OS in grade I breast cancer patients (HR = 3.46, 95%CI: 1.11–10.8, p = 0.0229)." (PMID 28051137, 2017). "Careful examination of these genes, their known roles in breast cancer, and our bioinformatics analysis of key pathways associated with TzR in vivo, suggested a potential key role of S100P." (PMID 27449296, 2016). "S100P protein has been reported to induce metastasis in rodent mammary model systems for breast cancer and to be associated with poor patient outcomes in breast, colon, lung cancer, and esophageal carcinoma." (PMID 23977152, 2013). "Through analyzing the KM plotter breast cancer database, our data further confirms that high expression of S100P is closely associated with poor RFS and OS in breast cancer patients, which indicates that S100P exhibits a strong link with tumor progression and prognosis in breast cancer." (PMID 33042844, 2020). "Furthermore, analysis of S100P in Oncomine demonstrated that S100P is strongly associated with breast cancer (p = 1.8E-94, average fold change = 10.9)." (PMID 27449296, 2016). "Results showed that ionizing radiation and estrogen affected the expression of those genes that encoded the S100 calcium-binding proteins such as S100P, S100A14, S100A2, S100A8, and S100A9 in the immortalized breast cancer cell line MCF-10F." (PMID 39594999, 2024). "S100P expression is significantly higher in BC tissue than in benign fibroadenoma, promoting the aggressive properties of breast cancer cells and metastasis." (PMID 39830522, 2024). "IRF5, MAP2K2 (MEK2), and S100P had concordant overexpressed mRNA in invasive breast cancer tissues and blood samples." (PMID 37445737, 2023). "We have recently shown that S100P also activates tissue plasminogen activator in breast cancer cells and that the C-terminal lysine of S100P is essential for enhancing cell migration and invasiveness." (PMID 37627296, 2023). "The protein expression of RAD52, RAD50, PBX2, MAP2K2 (MEK2), and S100P was also validated with immunohistochemistry in invasive breast cancer tumor tissues." (PMID 37445737, 2023). "The protein expression of FGF-2, RAD52, RAD50, PBX2, MAP2K2 (MEK2), and S100P was also validated with immunohistochemistry in invasive breast cancer tumor tissues." (PMID 37445737, 2023).
breast carcinoma (continued). "We observed overexpression of S100P in patients with all subtypes of breast cancer and overexpression of S100A7 in patients with luminal B, HER2 positive and basal breast cancer." (PMID 35087607, 2022). "S100P is an oncogenic event in many types of tumors, including pancreatic adenocarcinoma, breast cancer and ovarian cancer." (PMID 33815482, 2021). "The multiple repeat sequences of the lncRNA NORAD bind to and segregate S100P, and the S100P decoy function inhibits the migration, invasion, and metastasis in lung and breast cancers." (PMID 35071016, 2021). "Transfected Rama 37 cell clones and pools expressing wild-type S100P, the K95A, or ΔK95 mutant S100P proteins exhibited similar incidences of mammary tumour formation." (PMID 34680103, 2021). "Six out of twenty-two (27.27%) breast cancer patients showed strong staining of S100P, especially in Luminal B HER2+ subtype (4/4) (p = 0.041)." (PMID 33042844, 2020). "In conclusion, S100P enhances the proliferation, adhesion, migration, and invasion of breast cancer cells through the regulation of NF-κB, CCND1, E-cadherin and Vimentin." (PMID 33042844, 2020). "Immunohistochemistry was used to evaluate the expression level of S100P protein in 22 pairs (pre-chemo and post-chemo) of breast cancer tissue from patients who underwent neoadjuvant chemotherapy." (PMID 33042844, 2020). "We further used the KM plotter breast cancer database to explore the prognostic significance of S100P in breast cancer." (PMID 33042844, 2020). "The implication of S100P in the carcinogenesis and progression of breast cancer has also been reported." (PMID 33042844, 2020). "The invasive ability of breast cancer cells with low levels of S100P decreased significantly (T47D by 76.27%, p < 0.001; SK-BR-3 by 35.97%, p < 0.01)." (PMID 33042844, 2020). "C-terminally truncated form of S100P (t-S100P) is the major form of S100P and is exclusively located in the nucleus of breast cancer cells." (PMID 33042844, 2020). "The results indicated that expression levels of S100P in breast cancer were higher than those in fibroadenoma (p < 0.001)." (PMID 33042844, 2020). "To explore the influence of S100P on the invasion and migration of breast cancer cells, we conducted a transwell Matrigel assay and cell scratch experiment." (PMID 33042844, 2020). "Overexpression of S100P promotes breast cancer metastasis in animals and elevated levels in primary breast cancers are associated with poor patient outcomes." (PMID 32065231, 2020). "Other studies have since reported that activation of HER2 increases the expression of S100P in breast cancer cells." (PMID 33042844, 2020). "In the present study, the expression levels of S100P is extremely high in Luminal B HER2+ breast cancer, which is supported by previous studies." (PMID 33042844, 2020). "Our in vitro experiments showed that the knockdown of S100P suppressed the proliferation, adhesion, migrative and invasive abilities of T47D and SK-BR-3 breast cancer cells." (PMID 33042844, 2020). "Using T47D and SK-BR-3 breast cancer cell lines, the influence of S100P on cell behavior, biological function, and chemosensitivity was explored in vitro." (PMID 33042844, 2020). "The expression levels of S100P in 22 cases of breast cancer tissue samples before and after neoadjuvant chemotherapy, and 10 cases of breast fibroadenoma were detected by IHC." (PMID 33042844, 2020). "We conducted western blotting to unveil the mechanisms that S100P modulated the behaviors of breast cancer cells." (PMID 33042844, 2020). "The influence of S100P on the biological behavior and chemosensitivity of breast cancer cells was then investigated." (PMID 33042844, 2020). "Our results provide evidence that expression levels of S100P in breast cancer are significantly higher than those in fibroadenoma." (PMID 33042844, 2020). "The protein level of S100P in breast cancer tissue was significantly higher than in benign fibroadenoma (p < 0.001)." (PMID 33042844, 2020).